DEPTOR (DEP domain containing MTOR interacting protein)
Diseases named in the same sentence as DEPTOR in open-access papers (continued):
Sharing a sentence is not in itself a finding about the gene and the disease.
tumor (continued). "Therefore, defining the role of DEPTOR in specific cancer types, and whether it is acting as a tumor suppressor or an oncoprotein, would help to uncover the mechanism underlying tumorigenesis and tumor progression; thus, it would aid in the design of personalized treatments for cancer patients." (PMID 31685947, 2020). "The IHC assays showed that DEPTOR was overexpressed in 60% (66/110) of HCC tissues and presented low expression in 40% (44/110) of HCC tissues compared with adjacent non-tumor tissues." (PMID 31228948, 2019). "To explore the possible role of DEPTOR in HCC, we first detected its expression in a tissue microarray of 110 pairs of HCC and adjacent non-tumor tissues by IHC staining." (PMID 31228948, 2019). "Functional experiments demonstrated that DEPTOR silencing inhibited the proliferation and mobility of HCC cells in vitro and suppressed tumor growth and metastasis of HCC cells in vivo." (PMID 31228948, 2019). "Studies in cultured cells and zebrafish model show that UBTOR inhibits mTOR signaling by stabilizing the mTOR complex component DEPTOR, and ubtor gene disruption result in higher mTOR activity and aggravate HRAS(G12V) induced neoplasia in the zebrafish." (PMID 30080879, 2018). "β-TRCP has previously been shown to function as a tumor suppressor by targeting various oncoproteins such as β-catenin, CDC25A, FBXO5, IκB and DEP domain-containing mTOR-interacting protein (DEPTOR)." (PMID 29497989, 2018). "Here we report that the expression of DEPTOR is significantly reduced in tumor tissues derived from human patients with ESCC, and the downregulation of DEPTOR predicts a poor prognosis of ESCC patients." (PMID 26893358, 2016). "Knockout of DEPTOR, moreover contributed to enhanced tumor cell proliferation in VHL competent cells, whereas, restoration of DEPTOR expression in ccRCC cells inhibited tumor growth." (PMID 36831657, 2023). "Increased DEPTOR expression inhibited mTORC1 and alleviated the inhibitory feedback signal from mTORC1 to PI3K under normal conditions, resulting in a continuously activated PI3K–Akt signal that promoted the glycolytic metabolism in tumor cells." (PMID 37469018, 2023). "In tumor tissues, SPAG4 was overexpressed while ZBTB32 and DEPTOR were downregulated." (PMID 35095893, 2021). "Decreased expression of DEPTOR resulted the activation of AKT/mTOR pathway, which directly phosphorylated the downstream SGK1 and its substrate NDRG1, and thus promoted proliferation of tumor cells." (PMID 26893358, 2016). "Consistent with immunoblotting and qRT-PCR results, we found that DEPTOR is expressed in cytoplasm of non-cancerous cells, however its expression in paired tumor cells is greatly reduced." (PMID 26893358, 2016). "Thus, the pathway of DEPTOR knockdown leading to TORC1 activation, enhanced p21 expression and tumor regression is recapitulated in vivo." (PMID 25568666, 2014). "Under certain circumstances, DEPTOR overexpression inhibits S6K1, an mTORC1 substrate, and alleviates S6K-mediated IRS-1/PI3K (phosphoinositide 3 kinase)-dependent negative feedback to activate AKT, leading to cell survival, which facilitates tumor progression." (PMID 33854045, 2021). "As far as the role of DEPTOR in ESCC progression, we found that ectopic expression of DEPTOR inhibited the activation of AKT/mTOR pathway, and suppressed proliferation, migration, and invasion as well as in vivo tumor growth of ESCC cells with relatively low DEPTOR expression." (PMID 26893358, 2016). "Although a potential role for DEPTOR as an oncogene or a tumor suppressor has been investigated in different types of tumors, it has not been previously tested whether DEPTOR plays a role in the development of ESCC." (PMID 26893358, 2016).
cancer (41 papers, 2011 to 2026). A tumor composed of atypical neoplastic, often pleomorphic cells that invade other tissues. "Because mis-regulation of DEPTOR, an endogenous mTORC1 inhibitor, is associated with some cancers, we reconstituted mTORC1 with DEPTOR to understand its function." (PMID 34519269, 2021). "A similar reduction in DEPTOR IC50 was observed for the cancer-associated mTOR mutant A1459P." (PMID 34519269, 2021). "(B) Cancer-associated, hyperactive mutant mTORC1-A1459P also shows a decreased DEPTOR IC50." (PMID 34519269, 2021). "The IC50 of this DEPTOR mutant was comparable to the wild-type DEPTOR for both the wild-type mTORC1 and mTORC1 with an activating cancer-associated mTOR mutation (A1459P), so interaction between these S/T residues and mTORC1 is not important for inhibition by DEPTOR." (PMID 34519269, 2021). "Interestingly, in the analysis of microarray results in a GEO database, we found that the expression level of DEPTOR is associated with MYC in several types of cancer." (PMID 29472861, 2018). "DEPTOR, a naturally occurring inhibitor of mTOR, plays crucial roles in tumorigenesis and is frequently dysregulated in a variety of human cancers." (PMID 40169856, 2025). "These compounds act on the anabolic mTOR axis of the cancer cell, suppressing protein synthesis and rescuing the endogenous inhibitor DEPTOR." (PMID 36388131, 2022). "Our model simulations suggest that the relative effect of DEPTOR on cancer cell proliferation and survival depends on its expression level and other factors, including metabolic stress and AMPK activation level." (PMID 35078427, 2022). "In just over a decade since the discovery of DEPTOR, major roles have already been established in cancer, metabolism, and immunity explained by its ubiquitous tissue expression and modulation of fundamental cellular processes." (PMID 36413936, 2022). "While this scenario is usually associated with mutations within the PTEN/PI3K/AKT regulatory pathways, some cancers were shown to progress through dysregulation of DEPTOR inhibitory functions." (PMID 34634301, 2021). "As the mTOR pathway is constitutively activated in cancer, levels of DEPTOR are low in most tumours." (PMID 34519269, 2021). "DEPTOR has been characterized as a modulator of mTOR activity with a profound impact on metabolism and cancer." (PMID 34519268, 2021). "In few cancers, including multiple myeloma, DEPTOR is overexpressed and promotes cancer cell survival." (PMID 34519268, 2021). "The DEPTOR-mTORC1/2 axis has been shown to play an important, but a context dependent role in the regulation of proliferation and the survival of various cancer cells in cell culture settings." (PMID 31685947, 2020). "DEPTOR depletion can induce EMT in cancer cells and DEPTOR plays a critical role in EMT regulation by BMK1." (PMID 32998690, 2020). "First, since DEPTOR is frequently downregulated in various cancer types, likely transcriptionally repressed by both mTORC1 and mTORC2." (PMID 31685947, 2020). "Consistent with its inhibitory effect on mTORC1/2 (often activated in cancer), DEPTOR is frequently down-regulated in most tumours." (PMID 29330362, 2018). "DEPTOR expression is low in most cancers, consistent with the activation of the mTORC1 and mTORC2 pathways in many human cancers." (PMID 29670094, 2018). "The identification of DEPTOR as a direct mTOR inhibitor has led to a wave of studies investigating its role in cancer development and progression." (PMID 29330362, 2018). "Activation of mTOR signaling by feeding induced a clear mobility shift in DEPTOR protein levels, confirming that the protein is subject to a similar regulation in cancer cells and in normal tissues." (PMID 28462079, 2017). "The divergent impacts of DEPTOR in different cancers makes it vital to understand the detailed role of DEPTOR in specific cancer." (PMID 26893358, 2016).
cancer (continued). "In-depth studies on the role of DEPTOR localization and its differential regulation in cancers further needs to be studied in detail." (PMID 26992219, 2016). "Phosphorylation of DEPTOR by CK1α leads to βTrCP-mediated proteasomal degradation of DEPTOR resulting in activation of mTOR signaling, which is consistent with DEPTOR down-regulation and mTOR activation found in many cancers." (PMID 24904820, 2014). "Previous experiments highlighted the diverse functions of DEPTOR in cancer development." (PMID 39881385, 2025). "DEPTOR can promote or inhibit cancer in different types of tumors." (PMID 37469018, 2023). "It is well-documented that DEPTOR expression is low in most cancers, including those of the breast." (PMID 36388131, 2022). "How might a DEPTOR inhibitor differentially modify a cancer cell’s propensity to proliferate and persist?" (PMID 35078427, 2022). "DEPTOR levels are low in most cancers due to active PI3K signaling." (PMID 34519268, 2021). "However, in specific cancer types, such as multiple myeloma and T-cell acute lymphoblastic leukemia, DEPTOR exhibits oncogenic properties by activating AKT to alleviate the negative feedback effect of the mTORC1 substrate, S6K1, on IRS1/PI3K signaling." (PMID 33184290, 2020). "Our simulations confirm these observations and show that reduced DEPTOR can induce proliferation and cancer progression by releasing the inhibitory breaks on mTORC1/2, whereas upregulated DEPTOR may promote cancer by activating Akt instead." (PMID 29330362, 2018). "However, high levels of DEPTOR was reported to be essential for the survival of various cancer cells." (PMID 26992219, 2016). "Indeed, MLN4924, an indirect inhibitor of CRLs, induces autophagy in multiple cancer cell lines resulting from inactivating mTORC1 by the accumulation of DEPTOR and HIF1α." (PMID 27293474, 2016). "In some cases of ESCC patients that recruited into our study, DEPTOR expression just showed a minor difference between adjacent normal tissue and cancer tissue, this may be own to that the regulation of DEPTOR is complicated in different individual." (PMID 26893358, 2016). "DEPTOR accumulation induced the expression of the lipidated species of the LC3 autophagy marker (referred to as LC3-II), suggesting that GLN-mediated anti-cancer effects in the DSS/AOM mouse model might be associated with enhanced autophagy." (PMID 27144580, 2016). "DEPTOR is an endogenous inhibitor of mTOR complexes, de-regulated in cancers." (PMID 26992219, 2016). "Thus, it may be beneficial to administer compounds that enhance the stability of DEPTOR or its connection to mTOR, in an attempt to suppress mTOR and the growth, survival, and proliferation of cancer cells." (PMID 35078427, 2022). "This EPH receptor/SYK/DEPTOR mechanism, which bypasses the canonical pathway of mTOR activation, could potentially explain why so many cancers show constitutive mTOR activation without mutations in the PI3K/AKT pathway." (PMID 34634301, 2021). "In addition to acting as an inhibitor of mTOR, which is hyperactivated in the majority of human cancers, DEPTOR may also act as an oncogene in certain cancers." (PMID 31228948, 2019).
cancer (continued). "Therefore, CK1α might provide a therapeutic target for the treatment of cancers characterized by low DEPTOR levels and activation of mTOR signaling, leading to increasing DEPTOR levels, and inhibition of mTOR signaling." (PMID 24904820, 2014). "One mammalian-specific component of the mTORCs is DEPTOR (DEP domain-containing mTOR-interacting protein), which acts as an inhibitor of both mTORC1 and mTORC2, and some cancers are known to overproduce DEPTOR." (PMID 40243440, 2025). "Because DEPTOR affects the signalling of mTOR and PI3K, which are key modulators of cell growth, survival, and proliferation, the relationship between DEPTOR and cancer is a promising research focus." (PMID 35078427, 2022). "Recently, small molecule inhibitors have been designed to interrupt the DEPTOR PDZ/mTOR interaction and have shown selective cytotoxicity against this type of cancer." (PMID 34519269, 2021). "Several of the other genes are relevant to cancer—in addition to ERBB2, SKAP1 is an adaptor for Src, DEPTOR regulates the mTOR pathway and NRIP1 is an estrogen-receptor coregulator." (PMID 23260012, 2012). "In our study, we have noticed that DEPTOR inhibits the proliferation, migration and invasion of ESCC cells, future studies need to delineate whether DEPTOR regulate chemo-resistance in ESCC cells, as well as the role of DEPTOR in cancer stem cells of ESCC." (PMID 26893358, 2016). "Interestingly, among several well‐established CRL5 substrates that were examined, including integrin β1, p‐SRC (Y416), ATM, RPB1, EGFR, DEPTOR, and NOXA, only integrin β1 consistently accumulated across all cancer cell lines upon APC11 knockdown using two independent siRNAs targeting APC11." (PMID 41159544, 2026). "To determine the potential role of DEPTOR in progression of human ESCC, we firstly examined the expression of DEPTOR in cancer tissues from ESCC patients and paired adjacent non-cancerous tissues from the same patients." (PMID 26893358, 2016).
neurological disorders (1 paper, 2022). "Like the previous comparison, several of these transcripts, such as CELF5, DEPTOR, DLG2, OPTN and STX3, have been linked to brain functions and neurological disorders, supporting the fact that these hnRNP proteins can work in a network to regulate at least specific sets of targets." (PMID 36267332, 2022).
skeletal diseases (1 paper, 2022). "We recently demonstrated that parathyroid hormone (PTH)/PTH-related peptide (PTHrP) control the levels of DEPTOR, an inhibitor of the mechanistic target of rapamycin (mTOR), and that DEPTOR levels are altered in different skeletal diseases." (PMID 36726589, 2022).
DEPTOR also shares sentences with these, for which no sentence is quoted: breast (3 papers); differentiated thyroid carcinoma (3); thyroid cancer (3); Alzheimer disease (2); chronic myeloid leukemia (2); adenocarcinoma (1); alcoholic liver diseases (1); bipolar disorder (1); carcinoma in situ (1); cervical tumors (1); chordoma (1); degenerative disk disease (1); diabetes mellitus (1); dysplasia (1); endometrioid carcinoma (1); endometrioid ovarian cancer (1); endometriosis (1); gastritis (1); genetic diseases (1); gestational diabetes (1); head and neck squamous cell carcinoma (1); infection (1); leukemia (1); mental disorder (1); metastatic cancer (1); myeloid neoplasm (1); osteogenesis imperfecta (1); pancreatic adenocarcinoma (1); periodontitis (1); peripheral T-cell lymphomas (1).
A further 3 diseases each share a sentence with DEPTOR in 1 paper.